DPT (dermatopontin)
Diseases named in the same sentence as DPT in open-access papers (continued):
Sharing a sentence is not in itself a finding about the gene and the disease.
diabetes (1 paper, 2021). "Differentially regulated genes not overlapping with ERCB data also reflected diabetes-associated changes, such as extracellular matrix (ANGPTL4, TNN, DPT, COL9A2) or gestational diabetes (LAT2, HP, CXCL10, CD86, CD68, REN, SLC2A3, VCAM1)." (PMID 33923831, 2021).
dystrophinopathy (1 paper, 2012). "Collagen and dermatopontin should be considered as suitable biomarker candidates for evaluating the degree of fibrosis and tissue scaring in dystrophinopathy." (PMID 22614334, 2012).
Ehlers-Danlos syndrome (1 paper, 2024). The Ehlers–Danlos syndromes (EDS) are a clinically and genetically heterogeneous group of heritable connective tissue disorders (HCTDs) characterized by joint hypermobility, skin hyperextensibility, and tissue fragility. "DPT-knockout mice demonstrate an Ehlers-Danlos syndrome-like phenotype, such as skin fragility and impaired lateral arrangement of collagen microfibrils." (PMID 39199288, 2024).
fibrosis (1 paper, 2022). the formation of excess fibrous connective tissue in an organ or tissue in a reparative or reactive process. "In our study, DPT was up-regulated in liver fibrosis and was not significantly altered in kidney fibrosis and CD with fibrosis." (PMID 35159124, 2022).
glaucoma (1 paper, 2017). Increased pressure in the eyeball due to obstruction of the outflow of aqueous humor. "We unravel by WES a novel mutation in FOXC1 behind the ocular basic phenotype, and we propose a digenic model for the glaucoma phenotype along a mutation in the DPT gene and another digenic model for CHD involving yet a novel mutation in NFATC1." (PMID 28979898, 2017). "Our WES results identified a novel variant in the DPT gene inherited from the father and only present in the affected children with glaucoma but not in the healthy children." (PMID 28979898, 2017). "Additionally, there were no previous reports on the role of DPT in glaucoma, and only a few publications describe its expression and role in ocular development and pathology." (PMID 28979898, 2017).
cancer (28 papers, 2010 to 2025). A tumor composed of atypical neoplastic, often pleomorphic cells that invade other tissues. "The inhibition of DPT is associated with a range of pathologies including systemic sclerosis, uterine leiomyomas, cutaneous fibrosis, and several cancers." (PMID 33033513, 2020). "The most significant decreased gene in cancer samples is DPT, encoding protein Dermatopontin, an extracellular matrix protein with possible functions in cell-matrix interactions assembly, cell adhesion, wound healing, and positive modification of the growth inhibition activity of TGF-β1." (PMID 25970782, 2015). "Moreover, the expression of DPT has been linked to the development and prognosis of cancers." (PMID 38300311, 2024). "Recently, the influence of dermatopontin (DPT), which is an extracellular matrix protein, has been proposed in the development of cancer." (PMID 36774339, 2023). "It’s more interesting that when analyzing the origin of CSFs in separate cancer types, we found that CSFs were mainly transformed from DPT+ FBs in BC, CRC and OVC, while mainly from RGS5+ FBs in ICC." (PMID 36744260, 2023). "While genes such as PTH1R, DPT, DES, TCF21 and PDE2A are downregulated in many cancers, cell cycle associated genes, centromere proteins and kinesin family proteins are upregulated in all the cancer types we studied." (PMID 34728699, 2021). "For example, Parathyroid Hormone 1 Receptor (PTH1R) and collagen-binding Dermatopontin (DPT) were downregulated in all the 18 cancers." (PMID 34728699, 2021). "Genes that are associated with increased proliferation and invasion in several cancer types, such as DPT, ANPEP, and LRRN1, were among the most concordant DEG in this signature." (PMID 34311724, 2021). "Dermatopontin (DPT) is an extracellular matrix protein that regulates the metastatic phenotypes of many cancers." (PMID 33033513, 2020). "The DpT analogues bind iron and copper to generate oxidative stress in cancer cells, which induces lysosomal membrane permeabilization and results in these agents overcoming P-glycoprotein-mediated drug resistance." (PMID 27678372, 2016). "More recently, ligands of the di-2-pyridylketone thiosemicarbazone (DpT) class have demonstrated potent and selective anti-proliferative activity across multiple cancer-types in vivo, fueling studies aimed at dissecting their molecular mechanisms of action." (PMID 26125440, 2015). "Herein, we review recent research on the targeting of iron for cancer therapy, with emphasis on the novel DpT class of thiosemicarbazone iron chelators." (PMID 26125440, 2015). "Dermatopontin (DPT), a tyrosine-rich, acidic matricellular protein, has been implicated in several human cancers." (PMID 25149533, 2014). "In line with our observations, the downregulation of PTH1R and DPT could be important for most of the cancers." (PMID 34728699, 2021). "Since DPT can induce quiescence and increase TGF-β activity, which in turn acts as a tumor suppressor in many cancers, this finding may be in line with the introduction of a tumor suppressor role for DPT." (PMID 34094025, 2021). "Also, while 45% of higher-stage cancers showed increased expression of DPT, only 27% of lower-stage tumors (Stages I and II) demonstrated DPT overexpression." (PMID 34094025, 2021). "Furthermore, gain-of-function of DPT obviously suppressed the malignant biological properties of BC, such as cell growth, migration, and invasion, while knockout of DPT markedly increased cancer cell proliferation and metastasis." (PMID 36774339, 2023). "We constructed a multi-cancer fibroblast atlas, in which fibroblasts were classified into six clusters: BAMBI+ FBs, CLDN1+ FBs, COL11A1+ FBs, CXCL14+ FBs, DPT+ FBs and RGS5+ FBs." (PMID 36744260, 2023). "When the DEGs were further compared across four cancer types, we found five coregulated DEGs (upregulated DEGs: PCSK1N, CAMK2B, RUNDC3A and SNAP25; downregulated DEG: DPT) among four NECs." (PMID 35752613, 2022).
cancer (continued). "Another transcriptome profiling study in Chinese patients with GC revealed 36-fold higher expression of CDH1, while DPT and TGFBR2 showed decreased expression in cancer samples." (PMID 35625299, 2022). "DPT (dermatopontin) is a tyrosine-rich ECM protein, which principally takes a significant role in focal adhesion, matrix remodeling, and metastasis of cancer cells." (PMID 35966872, 2022). "In light of these findings, DPT may exhibit a different behaviour depending on the tissue in which it is expressed suggesting a tumour suppressor role in the colon, the tissue where cancer develops, and conversely, a promoter role of matrix remodelling and fibrosis in VAT." (PMID 36012487, 2022). "These merged DMxDE datasets suggest some known or previously reported/suspected cancer genes [PR: SPARCL1, NQO1, CST1, MELK1, DPT, FAM83A, MMP9; GB: FOXM1, TFAP2, GREM1, ITGA8, GRIA1, SLIT3] as well as many previously unreported genes/loci." (PMID 26683690, 2015). "We demonstrated that DPT was significantly down-regulated in 202 HCC clinical samples and that its expression level was closely correlated with cancer metastasis and patient prognosis." (PMID 25149533, 2014). "A few genes were found to be in both the cancer grading and staging signatures, such as CPS1, DES, GFRA3, TMED6 and DPT, indicating some biological relevance between cancer differentiation and progression." (PMID 21445269, 2011). "While this class of DpT analogues can effectively redox cycle after chelating Fe or Cu in cells and this participates in their anti-cancer activity, the lack of metabolites indicates that they are not significantly degraded by the redox stress that is induced." (PMID 26623727, 2015). "Nevertheless, the biological functions and molecular mechanisms of DPT in cancer metastasis have not been investigated." (PMID 25149533, 2014).
tumor (25 papers, 2014 to 2025). "Taken together, DPT expression is inversely correlated with somatic mutations as well as tumor grade, stage, and lymph node metastatic grade in both CHOL and LIHC." (PMID 38300311, 2024). "In contrast, ADAMDEC1+ Fibro, C3+ Fibro, CFD+ Fibro, DPT+ Fibro, Proliferating Fibro, and Myo Fibro were present in both tumor and normal tissues and were therefore classified under the Fibro group." (PMID 41031085, 2025). "After a comprehensive review of various studies, DPT emerged as the key target to influence tumor development and CHOL patients' prognosis." (PMID 38300311, 2024). "We also utilized the UALCAN database to explore the relationship between DPT expression and tumor grade, stage, and lymph node metastasis in CHOL and LIHC." (PMID 38300311, 2024). "In conclusion, our study revealed that DPT is under-expressed in BC, which results from DNMT3a-mediated aberrant hypermethylation of its promoter, and functions as a tumor suppressor." (PMID 36774339, 2023). "And in the validated cohort, increased DPT expression was negatively correlated with tumor size (P = 0.039)." (PMID 36774339, 2023). "Previous studies showed that ECM molecules such as periostin and dermatopontin were important in tumor initiation and progression." (PMID 35596183, 2022). "In this regard, a tumour suppressor role for DPT has been proposed, mainly based on its role in increasing the biological activity of TGF-β." (PMID 36012487, 2022). "Our IHC and proteomic data confirmed a high level of DPT expression in ACC while a low level in highly aggressive tumor-BL-TNBC." (PMID 35966872, 2022). "We show that DPT functions as a tumor suppressor in HCC and inhibits Wnt signaling through CXXC4 mediated β-catenin degradation." (PMID 33033513, 2020). "DPT is an extracellular matrix protein that regulates the metastatic phenotypes an array of human neoplasms." (PMID 33033513, 2020). "Currently, NDRG1 is being considered as an important oncogenic target of a new group of potent anti-tumor chemotherapeutics belonging to the DpT class, which include Dp44mT and DpC." (PMID 25860930, 2015). "In contrast, a number of genes described as tumor suppressors (among them osteoglycin, dermatopontin and secreted frizzled-related protein 4) were significantly upregulated after combination therapy." (PMID 25127546, 2014). "The DpT class of agents has been demonstrated by several international laboratories to possess potent and selective anti-tumor activity against a broad range of tumors in vitro and in vivo, with the compounds also being able to overcome P-glycoprotein-mediated resistance." (PMID 33334021, 2020). "DPT together with other decreased genes, which have been less investigated, might be potential tumor suppressor and need to be further studied." (PMID 25970782, 2015). "Our study provides new evidence for epigenetic control of tumor microenvironment, and suggests matricellular protein DPT may serve as a novel prognostic marker and act as a HCC metastasis suppressor." (PMID 25149533, 2014). "Apart from DpC, the analysis of the second generation DpT analogs also identified di-2-pyridylketone 4-ethyl-4-methyl-3-thiosemicarbazone (Dp4e4mT) as an agent with considerable promise in terms of its potency and selectivity against tumor cells in vitro and in vivo." (PMID 38239703, 2024). "Here, we showed that the expression of DPT was drastically downregulated in BC tissues whether in the TCGA cohort or in the validated cohort consisting of 100 paired BC tissues, and negatively correlated with tumor subtype and tumor size." (PMID 36774339, 2023). "ALDH2, ADH1B, ALDH3A2, DPT, EPHX2, and GATM were down-regulated in the tumor tissues, which is consistent with the expression of hub genes in the GSE3189 and GSE46517 datasets." (PMID 38378847, 2024). "The results indicated that DPT expression in CHOL and LIHC gradually decreased with increasing tumor grade, stage, and lymph node metastasis stage." (PMID 38300311, 2024).
tumor (continued). "DPT is an ECM protein that plays a role in localized adherence, and its downregulation accelerates PCa cell proliferation and tumor metastasis." (PMID 37251946, 2023). "DPT and SFRP2 were rarely expressed in normal epithelial cells and tumor immuno-microenvironment cells but were mainly expressed in fibroblasts from tumor tissues." (PMID 36104333, 2022). "It has been reported that DPT competes with decorin for its interaction with TGF-β 3, which regulates a range of pathological processes, including tumor progression, growth and survival." (PMID 33033513, 2020). "Meanwhile expression of gene DPT, SMOC2, GLP2R, FBLN5 and LMOD1 were down-regulated in tumor tissues." (PMID 25970782, 2015). "To further assess the relationship between the expression level of DPT and HCC metastasis, we collected normal liver, PCL, HCC and tumor thrombus tissues from the same individual patients and performed immunohistochemical staining." (PMID 25149533, 2014). "Dermatopontin (DPT), another gene strongly upregulated by the combination therapy, codes for a tumor suppressor." (PMID 25127546, 2014). "FR exhibited a high level of basement membrane proteins and fibroblast lineage markers (COL4A1, FBLN5, DCN, DPT) and is enriched for ECM organization, wound-healing, and cell adhension pathways, suggesting a potential shared mechanism between tumor-surrounding stroma and tissue repair." (PMID 39870619, 2025). "Given that CAFs are reported to be an important stromal component and are critically involved in tumor progression, we reclustered the CAFs and further categorized them into two main types: inflammatory CAFs (iCAFs; CFD, CKB, and DPT) and myoblastic CAFs (myCAFs; INHBA, SULF1, and COL8A1)." (PMID 36725337, 2023). "Furthermore, the highly expressed DEGs of fibroblasts in LNM included immune-related genes (CCL21, CCL19, CCL2, and MYC), metabolism-related genes (STEAP4, FABP4, DPT, and APOE), and genes related to tumor proliferation and progression (RGS, CCN, and MYC)." (PMID 37221625, 2023). "We found a tendency towards upregulation of DPT mRNA expression in the VAT from patients with CC, suggesting that in this tumour-surrounding tissue, DPT may promote CC development by favouring a pro-inflammatory microenvironment." (PMID 36012487, 2022). "We then analyzed the mRNA and protein levels of DPT in paired BC tissues and matched non-cancerous breast tissues by qRT-PCR and western blotting, and found that DPT was downregulated in most BC (8 out of 10 matched tumor/normal tissues analyzed)." (PMID 36774339, 2023). "Of 38 studied cases, 14 (36.8%) showed underexpression of DPT mRNA in their tumoral tissues compared with corresponding tumor-free tissues, while 12 (31.6%) cases had no change in expression of DPT, and the other 12 (31.6%) tumors cases overexpressed the DPT gene." (PMID 34094025, 2021). "Most of the validated mRNAs provided unique information about tumor aggressiveness, however, three pairs of transcripts in the validated set of 23 were correlated (P‐values < 0.05): CCNA2 and TPX2 (r2 = 0.61); SRD5A2 and DPT (r2 = 0.56); and SRD5A2 and FBLN1 (r2 = 0.73)." (PMID 28145099, 2017). "We first examined DPT expression in 202 HCC samples by immunohistochemical staining and found that DPT expression was significantly down-regulated and was closely related to indicators of tumor metastasis, such as vascular invasion and tumor thrombosis, and to patient prognosis." (PMID 25149533, 2014).
infection (3 papers, 2012 to 2025). The state of being infected such as from the introduction of a foreign agent such as serum, vaccine, antigenic substance or organism. "FREP 2 and 3, coagulation factor IX, dermatopontin, dual oxidase, galectin 4, MIF, peroxiredoxin, superoxide dismutase Cu-Zn, and heat-shock protein 70 all exhibited increased expression in snails that successfully resisted infection compared to those that were infected by S. mansoni." (PMID 22479663, 2012).
adenocarcinoma (2 papers, 2015 to 2022). A common cancer characterized by the presence of malignant glandular cells. "In vitro studies in the adenocarcinoma HT-29 cell line were performed to analyse the impact of pro- and anti-inflammatory mediators on the transcript levels of DPT as well as the effect of DPT on ECM remodelling and inflammation." (PMID 36012487, 2022). "Of the canonical changes noted, promoter (PR) DM loci with reciprocal changes in expression in adenocarcinomas included HBEGF, AGER, PTPRM, DPT, CST1, MELK; DM GB loci with concordant changes in expression included FOXM1, FERMT1, SLC7A5, and FAP genes." (PMID 26683690, 2015).
DPT also shares sentences with these, for which no sentence is quoted: Uterine leiomyoma (4 papers); hepatic disorders (2); liver cirrhosis (2); atrial fibrillation (1); biliary atresia (1); cardiomyopathy (1); cervical cancer (1); cholangiocarcinoma (1); connective tissue disorder (1); COVID-19 (1); Duchenne muscular dystrophy (1); endometrial cancer (1); filariasis (1); gestational diabetes (1); Heart Disease (1); hypothyroidism (1); immune disorder (1); Infertility (1); laryngeal carcinoma (1); liver fibrosis (1); lymph node metastasis (1); Meniere disease (1); metastatic melanoma (1); neuroblastoma (1); osteoarthritis (1); osteosarcoma (1); parasitic infections (1); protein misfolding disorders (1); stomach cancers (1); systemic lupus erythematosus (1).
A further 1 disease shares a sentence with DPT in 1 paper.